CRP (C-reactive protein)
Diseases named in the same sentence as CRP in open-access papers (continued):
Sharing a sentence is not in itself a finding about the gene and the disease.
psychological distress (40 papers, 2008 to 2025). "Even after controlling for factors that strongly correlate with CRP, such as BMI, socioeconomic status, life events, substance use, and psychological distress, interpersonal stress involving family or friends is associated with increased CRP levels." (PMID 38339813, 2024). "Clearly, more studies are warranted to explore the association between CRP and psychological distress during adolescence and investigate potential sex differences." (PMID 35360574, 2022). "In boys, we found a prospective association between CRP at baseline and psychological distress at follow-up where an increase of 0.01 mg/L in CRP indicated an increase of 0.021 units in HSCL-10 at follow-up." (PMID 35360574, 2022). "Large population studies that have detected statistically significant associations between CRP and psychological distress in adults used sample sizes of approximately 70,000 participants." (PMID 35360574, 2022). "While the pathogenesis of mental illness is not clearly understood, the association of CRP, sTNFR-II, and mental health symptoms in the study population suggests an association between a proinflammatory state and psychological distress in the population." (PMID 34112126, 2021). "As expected, psychological distress was negatively associated with perceived neighbourhood cohesion (rho = − 0.13, p < 0.001) and positively associated with CRP (rho = 0.09, p < 0.001)." (PMID 30805881, 2019). "In this model, CRP had a significant main effect on psychological distress, with higher CRP scores being associated with scores ≥ 4 on the GHQ (OR 1.33, 95% CI 1.14–1.55, p < 0.001)." (PMID 30805881, 2019). "We examined associations between trauma exposure, MDD, PTSD, emotion dysregulation, and CRP among 40 African-American women with T2DM recruited from an urban hospital." (PMID 27493807, 2016). "One might speculate that low body fat percentage and physical activity among boys protects against the deleterious effects of CRP-associated inflammation on psychological distress in the long-run." (PMID 35360574, 2022). "In our study, we selected psychological distress, QoL, and C-reactive protein (CRP) as key variables based on previous research evidence." (PMID 40966684, 2025). "Another COVID-19 study found a positive correlation between loneliness and C-reactive protein (CRP) levels—a marker of systemic inflammation—even after controlling for prior psychological distress and other relevant covariates." (PMID 38684565, 2025). "The psychological distress score was correlated with CRP concentration after targeted therapy (R2=0.058; P=.03)." (PMID 40966684, 2025). "In this study, psychological distress was positively correlated with concentrations of CRP (R2=0.058; P=.03) and negatively correlated with MMSE scores (R2=0.426; P<.001)." (PMID 40966684, 2025). "Additional meta-analytic results of 19 randomized control trials identified that psychosocial interventions most effectively reduced CRP in individuals experiencing psychological distress." (PMID 36937648, 2023). "According to our study, increased levels of CRP and TGF-α are associated with the development of more psychological distress across adolescence in boys." (PMID 35360574, 2022). "This indicates that the effect of CRP on psychological distress is dependent upon body fat percentage and physical activity." (PMID 35360574, 2022). "Psychological distress, immune cell proportions, cytokines, CRP and serum cortisol were measured at baseline and during the exam period." (PMID 32242145, 2020). "Exacerbation of mood disturbances correlates with the level of many inflammatory markers: C reactive protein (CRP), IL-1, IL-2, IL-5, IL-6, IL-12, IL-13, TNF- α, Interferon-α." (PMID 33156872, 2020). "The inclusion of mood disturbance and sleep impairment, separately and combined, only slightly attenuated the association of FMS to CRP after adjustment for demographic and lifestyle factors (AOR = 1.01, CI 1.00, 1.01)." (PMID 28687081, 2017).
psychological distress (continued). "This is the first study to examine the complex relationships between trauma, psychiatric disorders, self-reported emotion dysregulation, and CRP and therefore more research with larger sample sizes is needed to replicate these findings." (PMID 27493807, 2016). "Because CRP correlates with psychological distress, we use it as a proxy variable to infer whether children aged 1 to 17 had higher stress levels in the years after the change in family structure than in the years before." (PMID 38339813, 2024). "It will also explore correlations between changes in psychological distress and CRP." (PMID 37790218, 2023). "No changes were observed in the associations between CRP and psychological distress following exclusion of participants with CRP > 10 mg/L." (PMID 36198766, 2022). "For example, in a prospective population-based study, subjects with high psychological distress at baseline were more than twice as likely to develop MetS than those with low psychological distress, even after adjusting for sociodemographic variables, health behaviors, and C-reactive protein." (PMID 32920774, 2021). "Next, we added the multiplicative interaction term between perceived neighbourhood cohesion and CRP to regression Models B and C to test whether inflammation and perceived neighbourhood cohesion interact to predict psychological distress." (PMID 30805881, 2019). "CRP–fatigue associations in the 61–98 group were robust to adjustment for GHQ, and hence do not appear to simply reflect a broader connection between inflammation and psychological distress." (PMID 28994356, 2018). "In this respect it is tempting to suggest that one link between psychological distress and cardiovascular disease may be raised levels of CRP." (PMID 18384670, 2008). "Previous studies have shown that the experience of negative life events may result in increased levels of pro-inflammatory markers, mainly IL-6 and CRP, via psychological distress (Baumeister, Akhtar, Ciufolini, Pariante, & Mondelli, 2016; Flouri, Francesconi, Papachristou, Midouhas, & Lewis, 2019)." (PMID 39618323, 2024). "Therefore, participants with high CRP may have a heightened stress response and impaired social perceptions contributing to pandemic psychological distress, including feelings of loneliness." (PMID 36198766, 2022). "Our outcome variable is the biomarker c-reactive protein (CRP), which correlates with psychological distress and is collected from blood samples." (PMID 38339813, 2024). "In this population-based longitudinal study among adolescents, boys with higher levels of CRP and TGF-α at baseline reported more psychological distress at two-year follow-up." (PMID 35360574, 2022). "Also, correlations between CRP protein levels and methylations of IL-6, CRP, and LINE-1 genes were detected after an 8-week yoga intervention in a community population of women reporting psychological distress." (PMID 37836535, 2023). "Furthermore, the interactions of ACEs with cortisol, CRP, and PGS were tested to understand the gene-environment and biology-environment interactions influencing psychological distress during the pandemic." (PMID 36198766, 2022). "However, as opposed to this, a study conducted to assess circulating inflammatory markers in healthy young adults also did not prove CRP to be statistically related to psychological distress, although CRP was correlated with fibrinogen." (PMID 37900445, 2023). "This shows that there is no direct causal relationship between CRP and MDD or psychological distress and that underlying inflammation caused by other diseases may be a more rational explanation for this association." (PMID 37996851, 2023). "However, another study of individuals reporting psychological distress found no significant reduction of IL-6, TNF-α, and CRP post intervention or at follow-up." (PMID 35648793, 2022).
ST Elevation Myocardial Infarction (40 papers, 2009 to 2025). A myocardial infarction that produces elevation in the ST segments of the ECG. "C-reactive protein velocity (CRPv) has been proposed as a very early and sensitive risk predictor in patients with ST-elevation myocardial infarction (STEMI)." (PMID 34884196, 2021). "Numerous studies have demonstrated that patients with STEMI exhibit significantly higher CRP levels compared to those with non–ST-elevation myocardial infarction (NSTEMI), highlighting the greater inflammatory burden associated with STEMI." (PMID 41303859, 2025). "C-reactive protein (CRP) apheresis has been introduced in ST-elevation myocardial infarction and cardiogenic shock." (PMID 39211771, 2024). "The CAR has also been suggested to be a more effective prognostic marker in predicting prognosis of patients with ST elevation myocardial infarction (STEMI) compared to C-reactive protein and albumin alone." (PMID 37834958, 2023). "Studies have shown that in patients undergoing PCI for the first ST elevation myocardial infarction, there is a clear relationship between the in-hospital CRP plasma concentration and the development of HF after infarction." (PMID 34869676, 2021). "Different research stresses that the C-reactive protein (CRP) is increased in ST-elevation myocardial infarction (STEMI) patients compared to healthy subjects." (PMID 32825327, 2020). "In addition, we examined the deposition of native and neoepitope-expressing CRP on the surface of microvesicles from the circulation of patients with ST-elevation myocardial infarction." (PMID 28112148, 2017). "C-reactive protein velocity (CRPv), defined as the change in wide-range CRP concentration divided by time, is an inflammatory biomarker associated with increased morbidity and mortality in patients with ST elevation myocardial infarction (STEMI) treated with primary percutaneous intervention (PCI)." (PMID 35054095, 2022). "For the meta-analysis, ST-elevation myocardial infarction (STEMI), non-ST-elevation myocardial infarction (NSTEMI), and UA were grouped according to hs-CRP levels." (PMID 34231707, 2021). "The levels of NT-proBNP, hs-CRP, and MMP-28 were significantly higher in patients with acute ST-elevation myocardial infarction (STEMI) than in patients with non-ST-elevation myocardial infarction (NSTEMI) (P < 0.01)." (PMID 32596395, 2020). "In a recent study, the IL-6 receptor (IL-6R) antagonist tocilizumab reduced C-reactive protein (CRP) and percutaneous coronary intervention (PCI)-related troponin T (TnT) release in patients with non-ST-elevation myocardial infarction (NSTEMI)." (PMID 30258440, 2018). "PTX3, IL-6 and hs-CRP were measured at predefined time points, at baseline(before percutaneous coronary intervention (PCI)), at 12 and 72 hours afterPCI in 161 patients with first-time ST elevation myocardial infarction(STEMI)." (PMID 32403934, 2020). "The ARMADA study evaluated anti-inflammatory effects of heparin and enoxaparin in Non-ST-Elevated Myocardial Infarction (Non-STEMI) and reported that inflammatory markers (CRP and von Willebrand factor) are affected more by LMWH compared to UFH." (PMID 26064103, 2015).
transient ischemic attack (40 papers, 2011 to 2025). A brief attack (from a few minutes to an hour) of cerebral dysfunction of vascular origin, with no persistent neurological deficit. "Previous studies showed that CRP concentrations were modestly associated with the risk of IS and transient ischemic attack (TIA) in middle-aged and elderly individuals." (PMID 25191699, 2014). "CRP has been shown to be associated with an increased risk of all-cause mortality in patients with acute IS, predicts further ischemic events in patients with transient ischemic attack, lacunar stroke or IS in general." (PMID 34685473, 2021). "Low-grade systemic inflammation, as reflected by elevated CRP levels, has also been identified as an independent predictor of recurrent ischemic events, particularly in patients with minor ischemic stroke or transient ischemic attack (TIA)." (PMID 41227149, 2025). "Manuela and his colleagues consider that CRP levels after a minor first cerebrovascular event (transient ischemic attack or lacunar stroke) can contribute to identifying patients at high risk of a second ischemic event." (PMID 36448063, 2022). "This study aimed to explore the clinical study of clopidogrel combined with Huoxue Tongluo prescription in improving transient ischemic attack (TIA) and the effect on MMP-9, Hcy, and CRP." (PMID 35399851, 2022).
emphysema (39 papers, 2007 to 2025). "Similarly, while previous literature suggested that sRAGE and fibrinogen are individually associated with emphysema, our analysis revealed that the combination of SP-D, CRP, sRAGE, and fibrinogen was more highly correlated." (PMID 28610627, 2017). "In certain types of emphysema, antitrypsin levels are elevated, in parallel with CRP levels, implying greater systemic inflammation, which translates to reduced antioxidant capacity and worse lung functions." (PMID 40508213, 2025). "Because the CRP had improved from 16.2 to 5.3 mg/L on the 18th day, the follow‐up CT was performed at this point, which revealed that the emphysema formation was disappearance." (PMID 39135772, 2024). "Emphysema had a significant inverse relationship with CRP and fibrinogen, while E/I MLD had an inverse association with CRP." (PMID 29458372, 2018). "A recent observational study revealed reduction in systemic inflammatory marker C-reactive protein (CRP) following lung sealant induced LVR in emphysema patients, which is now undergoing a large multicentre trial for validation." (PMID 25614834, 2014). "For instance, incorporating inflammatory markers (e.g., C-reactive protein and interleukin-6) or imaging modalities (e.g., CT-based emphysema quantification) could provide a more comprehensive understanding of disease progression and comorbidities." (PMID 39949428, 2025). "C-reactive protein (CRP), tumour necrosis factor alpha (TNF-alpha) and interleukin- (IL-) 6 and 8 are raised in COPD, with the latter two being associated with the progression of emphysema." (PMID 37509640, 2023). "Interestingly, McAllister et. al. reported that emphysema severity was an independent variable, over airways obstruction and the systemic inflammatory mediator CRP, for brachial PWV in patients with usual COPD." (PMID 21138571, 2010). "Meanwhile, compared to patients with emphysema and normal lungs, patients with CPFE had higher levels of serum inflammation, characterized by significantly elevated levels of WBC, CRP, IL-6, and fibrinogen." (PMID 40507634, 2025). "Whereas human clinical trials with autologous bone marrow-derived MSCs (BM-MSCs) demonstrated safety and reduced circulating levels of inflammatory marker C-reactive protein (CRP), beneficial effects on lung function in emphysema patients were limited." (PMID 34831082, 2021). "The results of univariate analysis revealed that four parameters, namely subcutaneous/mediastinal emphysema, CD4+/8+ ratio, and CRP and serum ferritin levels, were significantly different between the responsive and non-responsive groups." (PMID 31781564, 2019). "Nonemphysematous smokers had elevated CRP levels and worse lung function compared to emphysema patients with similar levels of antitrypsin." (PMID 40508213, 2025). "In non-severe patients, a positive correlation was found between severity of GGO, consolidation and emphysema and sex, tachypnea, chest x-ray (CXR) score on admission and laboratory parameters: CRP, D-dimer, ALT, lymphocyte count and lymphocyte/neutrophil ratio." (PMID 34015025, 2021). "It appears that assessment of MMP degraded collagen type I or type VI and total CRP are not the correct markers to evaluate emphysema in a broad population." (PMID 29202744, 2017). "In the present study, there was no relation between the structure related markers C1M and C6M or CRP with having significant emphysema or not." (PMID 29202744, 2017). "Inflammatory markers such as CRP were not elevated in emphysema progressors, nor were emphysema progressors more likely to have lower CD4 cell counts, lower CD4:CD8 ratios, or detectable HIV viral loads." (PMID 27902753, 2016). "IL-6 was significantly higher in smokers with emphysema than in the other two groups while TNF values were similar in all groups, and CRP tended to be higher in smokers with or without emphysema (ANOVA, p = 0.077)." (PMID 17822550, 2007).
emphysema (continued). "To test this hypothesis, we measured serum interleukine-6 (IL-6), tumor-necrosis factor (TNF), and C-reactive protein (CRP) in smokers with emphysema, smokers without emphysema, and in non smokers with normal lung function." (PMID 17822550, 2007).